TRIM59 (tripartite motif containing 59)
Diseases named in the same sentence as TRIM59 in open-access papers (continued):
Sharing a sentence is not in itself a finding about the gene and the disease.
breast cancer (continued). "Together, our results establish a positive correlation of augmented TRIM59 expression with breast cancer progression and survival." (PMID 30408026, 2018). "Downregulation of TRIM59 inhibits the progression of breast cancer." (PMID 38994350, 2024). "Elevated TRIM59 has also been detected in numerous malignancies, including breast cancer." (PMID 38994350, 2024). "Breast cancer-related in vitro experiments demonstrated that hsa-miR-148b-3p could inhibit tumor cell proliferation and promote breast cancer cell apoptosis by downregulating TRIM59." (PMID 36911413, 2023). "Based on a previous study, HUCMSCs-exo harboring miR-148b-3p could delay breast cancer progression through down-regulating TRIM59." (PMID 35428780, 2022). "In this study, we have demonstrated a previously unrecognized role of TRIM59 in breast cancer." (PMID 30408026, 2018). "Therefore, our data suggest a multifaceted function of TRIM59 in regulating breast cancer angiogenesis and metabolism, which will be further subjected to mechanistic dissection in follow-on studies in the near future." (PMID 30408026, 2018). "TRIM59 promoted breast cancer cell growth and migration/invasion both in vitro and in vivo." (PMID 30408026, 2018). "Here, we identify TRIM59, a protein in the E3 ligase family known to target ubiquitinated proteins for proteasomal or autophagic degradation, as a key component of a novel molecular mechanism in human breast cancer." (PMID 30408026, 2018). "Specifically, TRIM59-deleted breast cancer cells favor the amoeboid mode through (i) augmented activation of actomyosin contractile proteins MLC2 and ERM, (ii) excessive formation of E-cadherin-mediated focal adhesion, and (iii) the suppression of metastasis-associated Wnt/β-catenin signaling." (PMID 30408026, 2018). "We further analyzed the expression of TRIM59 in human breast cancer patient lymph node metastases versus primary tumor with both RNA sequencing dataset analysis (GSE30480) and IHC staining on patient tissue array samples (paired primary versus metastatic tissues from the same patient)." (PMID 30408026, 2018). "Importantly, we showed that TRIM59 was essential for the transition of breast cancer cells between mesenchymal and amoeboid movements." (PMID 30408026, 2018). "Thus, our data demonstrate a positive correlation between TRIM59 expression and breast cancer metastasis." (PMID 30408026, 2018). "Also, TRIM59 is highly upregulated in breast, colorectal, gastric and pancreatic cancer and in several breast cancer and colorectal cancer cell lines, and this upregulation is correlated with lymph node metastasis in breast cancer and with poor prognosis for patients." (PMID 33670160, 2021). "To test whether PDCD10-ROCK signaling is downstream of TRIM59 but upstream of MLC/ERM to impact breast cancer cells’ contractility, we performed functional rescue experiments by using a ROCK inhibitor (Y-27632) or through the lentivirus-mediated stable expression of PDCD10 in TRIM59 KO MCF7 cells." (PMID 30408026, 2018). "TRIM59 suppresses K63 ubiquitination by RNFT1 and PDCD10 degradation by p62-mediated selective autophagy, which promotes migration of breast cancer cells." (PMID 36202787, 2022). "Similar to TRIM59, PDCD10 expression was correlated with shortened breast cancer patient survival, suggesting a potential pro-oncogenic role of both TRIM59 and PDCD10 in breast cancer." (PMID 30408026, 2018). "In parallel, we stably overexpressed TRIM59 by about 20-fold in MDA-MB-231, a breast cancer cell line with relatively low TRIM59 expression." (PMID 30408026, 2018). "TRIM59 was found overexpressed in human breast cancer samples, compared to paired nontumor samples, and was associated with poor prognosis for these BC patients." (PMID 34208621, 2021).
breast cancer (continued). "Tan and colleagues showed that TRIM59 stabilizes the apoptosis-related protein PDCD10 by inhibiting its ubiquitination and subsequent P62-selective autophagic degradation; in turn, this promoted RhoA and ROCK1 activation and metastasis of breast cancer cells." (PMID 33194618, 2020). "Most TRIM proteins, such as TRIM44 and TRIM59, exhibit a cancer-promoting role, consistently upregulated across several cancer types, whereas TRIM proteins like TRIM16 suppress cell proliferation and metastasis in neuroblastoma, melanoma, ovarian cancer and breast cancer." (PMID 39451518, 2024). "TRIM59 promotes neuroblastoma through the Wnt/beta-catenin and PI3K/AKT signaling pathways, accelerates bladder cancer via the TGF-beta/Smad2/3 signaling pathway, and facilitates breast cancer, cholangiocarcinoma, and ovarian cancer through the PI3K/AKT signaling pathway." (PMID 32133014, 2020). "Hence, a therapeutic intervention that interrupts the functional interplays between TRIM59 and PDCD10 might provide a promising strategy to treat breast cancer and CCM." (PMID 30408026, 2018). "Notably, TRIM59 protein levels were positively correlated with the pathologic grades of breast cancer (Grade I, n = 18; Grade I–II, n = 26; Grade II and higher, n = 110) and were slightly higher in estrogen receptor (ER)-negative breast cancer." (PMID 30408026, 2018). "Besides the observation of TRIM59 in the regulation of breast cancer cell survival and mode of cancer cell migration and metastasis, our unbiased RPPA study revealed that other critical oncogenic pathways are altered upon TRIM59 depletion in breast cancer cells." (PMID 30408026, 2018).
gastric cancer (15 papers, 2017 to 2026). A primary or metastatic malignant neoplasm involving the stomach. "TRIM59 levels were decreased in human gastric cancer tissues, which was associated with a favorable prognosis in patients." (PMID 39768197, 2024). "In our study, the associations between TRIM59 variant genotypes and clinicopathologic characteristics of gastric cancer patients were also evaluated." (PMID 28009992, 2017). "Tripartite motif 59 (TRIM59) is a novel oncogenic driver in gastric cancer (GC) that is implicated in disease progression as well as dismal survival." (PMID 28009992, 2017). "Lastly, TRIM59 upregulation has been observed in gastric cancer, non-small cell lung cancer and osteosarcoma." (PMID 34065345, 2021). "Zhou found that TRIM59 was highly expressed in gastric cancer and was significantly related to the prognosis of the patients base on bioinformatics retrieval and analysis of multiple databases." (PMID 31770215, 2019). "Recent research revealed that TRIM59 expression was correlated positively with the pathologic grade of gastric cancer." (PMID 28009992, 2017). "TRIM59, attracted attention when it was found to be highly overexpressed in gastric cancer." (PMID 33670160, 2021). "Furthermore, the expression levels of TRIM59 mRNA and protein in clinical samples, tissue chips and gastric cancer cell lines were detected." (PMID 31770215, 2019). "TRIM59, a member of the TRIM ubiquitin ligase family, has long been considered a tumor marker in association with tumor progression and metastasis in several tumor types, such as non-small cell lung cancer, gastric cancer, osteosarcoma, and cervical cancer." (PMID 31600735, 2019). "Additionally, in gastric cancer, TRIM59 was highly expressed in tumor tissues and gastric cancer cell lines (AGS and MKN45), which promoted the growth of tumors in vivo in BALB/c nude mice bearing subcutaneous xenografts and the proliferation of cancer cells in vitro." (PMID 39768197, 2024). "As supported by analyses of gastric cancer patient tissues and in vitro experiments using human gastric cancer cell lines BGC823 and SGC7901, TRIM59 promoted the degradation of TRAF6, a member of the TRAF family, via ubiquitination, thus inhibiting the NF-κB signaling pathway." (PMID 39768197, 2024).
non-small cell lung carcinoma (10 papers, 2015 to 2025). A group of at least three distinct histological types of lung cancer, including non-small cell squamous cell carcinoma, adenocarcinoma, and large cell carcinoma. "Conversely, a distinct protein called TRIM59 has been observed in non-small-cell lung cancer (NSCLC) cells to enhance glycolytic activity by inducing PTEN ubiquitination." (PMID 38202657, 2023). "We found that TRIM59 expression level in non-small cell lung cancer (NSCLC) was significantly increased through second-generation sequencing." (PMID 31948534, 2020). "TRIM59 protein levels are significantly high in non-small cell lung carcinoma (NSCLC) and its expression is significantly elevated in cervical cancers, epithelial ovarian cancer (EOC), cholangiocarcinoma (CCA) tissues and cells, breast cancer, and CRC." (PMID 31137886, 2019). "Based on bioinformatics analysis, Hao found that the expression level of TRIM59 in NSCLC (non-small cell lung cancer) was significantly increased." (PMID 31770215, 2019). "We previous reported that TRIM59 protein was significantly increased in various non-small cell lung cancer cells." (PMID 28211536, 2017). "Notably, extensive research has shown that TRIM59 serves as an oncogene in multiple types of human cancers, including ovarian, gastric, pancreatic, and non-small cell lung cancers." (PMID 40796729, 2025).
Alzheimer disease (7 papers, 2018 to 2025). A progressive, neurodegenerative disease characterized by loss of function and death of nerve cells in several areas of the brain leading to loss of cognitive function such as memory and language. "In younger early-onset Alzheimer’s disease patients, rapid hypermethylation on TRIM59 resulted in a lower age prediction accuracy, with an MAE of 12.2 years, as opposed to 5.7 years for healthy controls." (PMID 40243941, 2025). "They found hypermethylation and decreased prediction accuracy for TRIM59 in early-onset Alzheimer’s disease patients." (PMID 37621446, 2023). "Our previous study revealed aberrant hypermethylation of TRIM59 in early-onset Alzheimer’s disease patients and in Graves’ disease patients." (PMID 29466246, 2018). "However, the CpGs in TRIM59 showed hypermethylation in the group of early onset Alzheimer’s disease as well as Graves’ disease patients while the CpGs in FHL2 showed hypomethylation in the latter." (PMID 37621446, 2023). "Therefore, based on the transcriptomic data of fEOAD patients, in this study, we present the genetic networks for hypermethylated KLF14 and TRIM59 with their downstream signaling pathways, potentially relevant in the pathology of Alzheimer's disease." (PMID 29849909, 2018). "They reported aberrant hypermethylation and decreased prediction accuracy of chronological age for TRIM59 and KLF14 markers in the group of early onset Alzheimer’s disease." (PMID 32661599, 2020).
colorectal cancer (7 papers, 2019 to 2024). A primary or metastatic malignant neoplasm that affects the colon or rectum. "The functional and molecular mechanisms by which TRIM59 affects the occurrence and development of colorectal cancer (CRC) through macrophages are still not well understood." (PMID 38992114, 2024). "In colorectal cancer and cholangiocarcinoma, TRIM59 was shown to promote proliferation, but this was thought to be through the PI3K/AKT or PI3K/AKT/mTOR signaling pathway, respectively." (PMID 34065345, 2021). "In addition, other studies have shown that TRIM59 promotes cell proliferation, invasion, and migration in colorectal cancer through the PI3K/AKT pathway." (PMID 36249749, 2022). "Additionally, in cholangiocarcinoma and colorectal cancer, TRIM59 was demonstrated to promote cellular proliferation." (PMID 34065345, 2021). "Sun detected TRIM59 in 90 cases of colorectal cancer by qRT-PCR." (PMID 31770215, 2019). "Additionally, the activated pathway can affect other oncogenes, such as doublecortin-like kinase (DCLK1), G protein-coupled receptor 56 (GPR56) and tripartite motif-containing 59 (TRIM59), and promote the migration and invasion of colorectal cancer (CRC) cells." (PMID 36632627, 2022). "It was found that the expression of TRIM59 in colorectal cancer tissue was significantly higher than that in non-cancer tissue, and the high expression of TRIM59 was significantly correlated with TNM stage, lymph node metastasis, depth of invasion and distant metastasis." (PMID 31770215, 2019).
prostate carcinoma (7 papers, 2015 to 2025). A carcinoma that arises from epithelial cells of the prostate gland. "For instance, TRIM59 is highly expressed and acts as an early signal transducer of Ras signaling pathway in prostate cancer (CaP) mouse models, whereas the silencing of TRIM59 results in inhibition of cell growth and S-phase arrest in CaP cells." (PMID 31820796, 2019). "TRIM59 was previously reported to act as a proto-oncogene that affects both Ras and RB signal pathways in prostate cancer models." (PMID 28211536, 2017). "As TRIM59 has been reported to act as a proto-oncogene that affects both Ras and RB signal pathways in prostate cancer models, we here focused on TRIM59 in NSCLC for further research." (PMID 26599082, 2015). "As TRIM59 has been reported to act as a proto-oncogene that affects both Ras and RB signal pathways in prostate cancer models, we here focused on the role of TRIM59 in the regulation of NSCLC cell proliferation and migration." (PMID 26599082, 2015). "Notably, TRIM59 has been observed to activate the Ras and Rb signaling pathways, thereby facilitating the progression of prostate cancer." (PMID 38062041, 2023).
bladder cancer (6 papers, 2019 to 2025). "Fourteen TRIM family proteins were associated with bladder cancer (tumor-promoting: TRIM9, TRIM25, TRIM26, TRIM28, TRIM29, TRIM59, TRIM65, and TRIM66; tumor-suppressive: TRIM19 and TRIM38)." (PMID 40723250, 2025). "They found that ITGB8/TRIM59/AKT/mTOR/glycolysis pathways were upregulated in bladder cancers with soft tumor cells." (PMID 40723250, 2025). "A recent study highlighted the considerable upregulation of TRIM59 in recurrent bladder cancer, involving the F-actin/ITGB8/TRIM59/AKT/mTOR/glycolysis pathways." (PMID 40796729, 2025). "TRIM59, which has an oncogenic role in both kidney cancers and bladder cancers, also has an oncogenic activity in CRPC." (PMID 40723250, 2025). "Silencing of Trim59 attenuates migration and invasion of bladder cancer cells while the presence of TGF-β1 relieves the suppressive effect of Trim59 knock-out." (PMID 31842336, 2019). "The TGF-β/Smad2/3 signaling pathway was suppressed by silencing Trim59 in bladder cancer." (PMID 35458126, 2022). "Trim59, the expression of which is upregulated in bladder tumors, promotes proliferation, EMT, migration, and invasion of bladder cancer cells." (PMID 31842336, 2019).
gastric tumor (6 papers, 2015 to 2024). "Emerging clinical evidence shows that TRIM59 were frequently up-regulated in tumor tissues compared with noncancerous tissues from breast and gastric tumors, where increased levels were correlated with advanced clinical stages and reduced survival among cancer patients." (PMID 32867817, 2020).